YTHDF2 (YTH N6-methyladenosine RNA binding protein F2)
Diseases named in the same sentence as YTHDF2 in open-access papers (continued):
Sharing a sentence is not in itself a finding about the gene and the disease.
HCMV infection (1 paper, 2022). "It was observed that the mRNA levels of METTL3, METTL14, YTHDF1, YTHDF2, and YTHDF3 were significantly increased in HAECs following HCMV infection." (PMID 35359726, 2022).
Hepatic fibrosis (1 paper, 2025). The presence of excessive fibrous connective tissue in the liver. "A preprint reported that METTL3 promoted the progression of hepatic fibrosis through YTHDF2-mediated silencing of GPR161 in a m6A-dependent manner." (PMID 40100806, 2025). "CircABHD3 promotes EMT and mitochondrial impairment via facilitating YTHDF2-mediated degradation of YPEL3 mRNA and activating downstream β-catenin signaling, thus exacerbating hepatic fibrosis." (PMID 40100806, 2025). "Taken together, we firstly demonstrated that MEOX1-regulated circABHD3 exacerbated hepatic fibrosis via promoting EMT and mitochondrial through suppression of YPEL3-mediated inactivation of β-catenin signaling in a YTHDF2-dependent manner." (PMID 40100806, 2025). "Subsequently, circABHD3 promoted YTHDF2-dependent recognition of YPEL3 mRNA to destabilize YPEL3 mRNA to reduce its expression and activate β-catenin signaling, thus exacerbating hepatic fibrosis." (PMID 40100806, 2025). "MEOX1-mediated generation of circABHD3 promotes EMT and mitochondrial impairment by enhancing YTHDF2-mediated degradation of YPEL3 mRNA and activating downstream β-catenin signaling, thus exacerbating hepatic fibrosis." (PMID 40100806, 2025). "We found that circABHD3 facilitated the decay of YPEL3 mRNA in a m6A/YTHDF2 dependent manner, leading to GSK-3β downregulation and inactivation of β-catenin signaling in liver fibrosis." (PMID 40100806, 2025). "Therefore, circABHD3 destabilized YPEL3 mRNA through YTHDF2 in a m6A-dependent manner, thus promoting EMT and hepatic fibrosis." (PMID 40100806, 2025).
Hepatitis (1 paper, 2025). Inflammation of the liver. "In conclusion, the rapid turnover of YTHDF1, YTHDF2, and YTHDF3 proteins during early ConA-induced hepatitis emerges as a hallmark of risk, suggesting their potential as crucial inflammation indicators in immune-mediated hepatitis." (PMID 40092485, 2025). "Initially, we investigated the protein expression of m6A readers, YTHDF1, YTHDF2, and YTHDF3, during the early stage of ConA-induced hepatitis and found that they were dramatically decreased in the liver." (PMID 40092485, 2025).
hepatitis B virus infection (1 paper, 2023). A viral infection caused by the hepatitis B virus. "Upon hepatitis B virus infection, YTHDF2 O-GlcNAcylation is found to be increased, which enhances its protein stability." (PMID 37086786, 2023).
HIV-1 infection (1 paper, 2016). The type species of lentivirus and the etiologic agent of acquired immunodeficiency syndrome (AIDS). "Indeed, we observed a unique high peak within the rev gene of HIV-1 RNA bound by YTHDF1, while YTHDF1 and YTHDF2 appear to have similar inhibitory effects on HIV-1 infection." (PMID 27371828, 2016).
hyperlipidemia (1 paper, 2021). "Therefore, it is reasonable to assume that FTO regulates the stability of CD36 mRNA via YTHDF2 dependent on the m6A modification in hyperlipidemia and PA-induced cardiomyocyte inflammation." (PMID 34881240, 2021).
Hypertension (1 paper, 2025). The presence of chronic increased pressure in the systemic arterial system. "YTHDF2 knockdown and NCOA4 overexpression acted synergistically to exacerbate ferroptosis, both in trophoblasts and in a PE mouse model, leading to aggravated hypertension, proteinuria, and fetal growth restriction, which were partially reversed by Fer-1." (PMID 41257944, 2025).
inflammatory bowel disease (1 paper, 2024). A spectrum of small and large bowel inflammatory diseases of unknown etiology. "YTHDF2 expression strongly correlates with the development of inflammatory bowel disease (IBD)." (PMID 38528957, 2024).
latent infection (1 paper, 2023). "To further determine the involvement of YTHDF2 in degradation of TYK2 mRNA, we monitored the protein levels of TYK2 after silencing YTHDF2 in both latent infection and after reactivation." (PMID 36918845, 2023).
low grade glioma (1 paper, 2022). A grade I or grade II glioma arising from the central nervous system. "However, the effects of YTHDF2 on the prognosis of low-grade gliomas (LGGs) and its correlation with tumor immune infiltration are unclear." (PMID 35661004, 2022).
mastitis (1 paper, 2025). Inflammation of breast tissue during lactation or postpartum due to an obstructed duct or infection. "This trend was further confirmed by transcriptomic data from milk samples of cows with subclinical mastitis and blood samples from cows infected with S. aureus, providing additional evidence for the downregulation of YTHDF2 during S. aureus infection." (PMID 40521032, 2025). "Given this observed reduction in YTHDF2 expression during S. aureus-induced mastitis, its potential regulatory role in apoptosis was investigated through both knockdown and overexpression experiments in Mac-T cells." (PMID 40521032, 2025). "Given its role in mRNA stability and degradation, YTHDF2 may regulate immune responses in bovine mammary epithelial cells during S. aureus infection, and may play a critical role in modulating the inflammation and apoptosis observed in mastitis." (PMID 40521032, 2025). "By modulating ROS levels and maintaining mitochondrial membrane potential, YTHDF2 protects cells from oxidative stress and apoptosis, highlighting its essential role in mitigating S. aureus-induced mitochondrial dysfunction and ensuring cellular homeostasis during mastitis." (PMID 40521032, 2025).
metastatic disease (1 paper, 2025). "Mechanistic data uncover a novel PDE1A/YTHDF2/STAT3 axis driving NSCLC metastasis and suggest potential therapeutic strategies for metastatic disease." (PMID 40704992, 2025).
microcephaly (1 paper, 2025). A congenital or acquired developmental disorder in which the circumference of the head is smaller than normal for the person's age and sex. "Further, the m6A‐labeled mRNA flavivirus ZIKA is associated with severe congenital microcephaly, with YTHDF2 found to bind and destabilize viral RNA." (PMID 39887636, 2025). "Based on these collective findings, we propose a model in which YTHDF2 loss‐of‐function results in microcephaly and possibly mortality, by increasing stability of m6A‐labeled RNAs resulting in extended cell‐cycle progression and a reduction in neurogenesis." (PMID 39887636, 2025). "Together, the knockdown and mRNA overexpression zebrafish models provide evidence that increased dosage of YTHDF2 is associated with DM while its loss leads to microcephaly." (PMID 39887636, 2025).
myeloid leukemia (1 paper, 2021). A clonal proliferation of myeloid cells and their precursors in the bone marrow, peripheral blood, and spleen. "YTHDF2 is a reader of N6-methyladenosine (m6A) on RNA and plays a critical role in the initiation and propagation of myeloid leukemia; however, whether YTHDF2 controls the development of LUAD remains to be explored." (PMID 33980824, 2021).
nasopharyngeal carcinoma (1 paper, 2025). A carcinoma arising from the nasopharyngeal epithelium. "However, the role of YTH N6-methyladenosine RNA binding protein F2 (YTHDF2), an m6A ‘reader protein’, in nasopharyngeal carcinoma (NPC) is poorly understood." (PMID 41369154, 2025).
oral carcinoma (1 paper, 2025). "METTL3, a m6A writer, enhances c-MYC stability by modifying m6A levels in oral carcinoma, whereas YTHDF2, a m6A reader, promotes its degradation." (PMID 41167308, 2025).
osteomyelitis (1 paper, 2022). An acute or chronic inflammation of the bone and its structures due to infection with pyogenic bacteria. "We found that METTL3 was highly expressed and YTHDF2 was expressed at low levels in osteomyelitis samples and validated this finding in a rat model of osteomyelitis." (PMID 36544487, 2022). "It is suggested that METTL3 and YTHDF2 may be involved in promoting osteogenic differentiation and attenuating the inflammatory response in the inflammatory environment of osteomyelitis, making them potential therapeutic targets." (PMID 36544487, 2022). "The qRT‒PCR results showed that the mRNA expression of METTL3, YTHDC1, RBM15B, LRPPRC and CBLL1 in osteomyelitis tissues was significantly increased, while that of YTHDF2 was significantly decreased (p < 0.05), which was consistent with the results of bioinformatics analysis." (PMID 36544487, 2022). "Based on the 6 significant m6A regulators with differential expression in the dataset, we further validated the expression of the 6 m6A regulators (METTL3, YTHDC1, YTHDF2, RBM15B, LRPPRC and CBLL1) in 10 osteomyelitis samples and 10 control samples by qRT‒PCR analysis." (PMID 36544487, 2022).
pancreatic ductal adenocarcinoma (1 paper, 2025). An infiltrating adenocarcinoma that arises from the epithelial cells of the pancreas. "Moreover, METTL13/METTL14/WTAP complexes and YTHDF2 facilitate PIK3CB mRNA and protein expression levels, significantly promoting the proliferation and migration of PTEN-deficient pancreatic ductal adenocarcinoma cells." (PMID 39806412, 2025).
polycystic ovary syndrome (1 paper, 2024). A disorder that manifests as multiple cysts on the ovaries. "YTHDF2 upregulates FOXO3 mRNA in GCs and contributes to the progression of non-obese polycystic ovary syndrome (PCOS) in women." (PMID 38397033, 2024).
rectal tumors (1 paper, 2021). "The significant up-regulation of YTHDF1, YTHDF2, and METTL3, and down-regulation of ALKBH5, YTHDC2, and METTL14 could be observed in the 6 rectal tumors (P < 0.05), indicating that these m6A regulators may be associated with progression of RC." (PMID 34149792, 2021).
retinal degeneration (1 paper, 2025). Degeneration of the retina. "The m6A reader YTHDF2 regulates retinal degeneration caused by aging, which is mediated by its target mRNAs Hspa12a and Islr2." (PMID 40371666, 2025). "Together, our results indicate that the m6A reader YTHDF2 regulates retinal degeneration caused by aging, which might provide important therapeutic potential for developing new treatment approaches against aging‐related vision loss." (PMID 40371666, 2025).
rhinitis (1 paper, 2025). An inflammation of the mucous membrane lining the nose, usually associated with nasal discharge. "Moreover, YTHDF2 protein expression was significantly elevated in 5-8F, CNE1 and HONE1 cells compared to NP69 cells, whereas it was higher in NPC tissues compared to rhinitis tissues although the difference was statistically non-significant." (PMID 41369154, 2025).
skin squamous cell carcinoma (1 paper, 2025). A carcinoma arising from the squamous cells of the epidermis. "Immunofluorescence analysis showed that YTHDF2 was lower in human skin squamous cell carcinoma samples (both stage 1 and stage 2) than in normal human epidermis." (PMID 41224760, 2025).
squamous cell carcinoma (1 paper, 2022). A carcinoma arising from squamous epithelial cells. "In GSEA of squamous cell carcinoma, there were no immune-related gene sets associated with YTHDF2." (PMID 36479088, 2022). "In adenocarcinoma, all eight immune checkpoints showed a negative relationship with YTHDF2, but only two immune checkpoints were negatively correlated in squamous cell carcinoma." (PMID 36479088, 2022). "In the squamous cell carcinoma group not receiving PD-1/PD-L1 inhibitor, the cutoff values of YTHDF1 and YTHDF2 were 45 and 40, respectively." (PMID 36479088, 2022).
sterility (1 paper, 2024). "The male mice with germ cell-specific knock-out of YTHDF2 exhibited sterility, with their sperm displaying abnormalities, reduced motility, and impaired fertilization capacity." (PMID 39342406, 2024). "However, it has also been proposed that deletion of YTHDF2 in mice has a partially permissive effect, resulting in female-specific sterility with little effect on males." (PMID 39342406, 2024).
synovitis (1 paper, 2023). Inflammation of a synovial membrane. "YTHDF2 has a high diagnostic value in the synovitis of OA and significantly influences the immune status of patients." (PMID 37496062, 2023). "The ceRNA network was constructed to explore the functions of ncRNAs of YTHDF2 in synovitis of OA, namely lncRNA and miRNA." (PMID 37496062, 2023).
triple-negative breast carcinoma (1 paper, 2024). An invasive breast carcinoma which is negative for expression of estrogen receptor (ER), progesterone receptor (PR), and human epidermal growth factor receptor 2 (HER2). "Additionally, it has been suggested that knockdown of YTHDF2 in triple-negative breast cancer cells induces proteotoxicity through ERS." (PMID 38776708, 2024). "Notably, YTHDF2 knockdown has been shown to promote ERS in MYC-induced triple-negative breast cancers, resulting in cytotoxicity and apoptosis." (PMID 38776708, 2024).
type I diabetes (1 paper, 2025). "Further investigations are warranted to define the role of YTHDF2 in the pathogenesis of SLE and type I diabetes." (PMID 41224760, 2025).
urinary system diseases (1 paper, 2021). "According to Open Targets evidence, YTHDF2 plays an important role in the immune system and urinary system diseases." (PMID 34512342, 2021).
tumor (348 papers, 2018 to 2026). "In tumor-associated macrophages (TAMs), YTHDF2 promotes a protumoral polarization state and suppresses antigen-presentation programs; myeloid-specific Ythdf2 loss reprograms TAMs toward antitumor phenotypes and enhances CD8+-mediated control in vivo." (PMID 41280938, 2025). "Tumor-specific Ythdf2 loss suppresses tumor growth, prolongs survival, recruits macrophages via CX3CL1, reduces glycolysis, enhances CD8+ T-cell mitochondrial respiration, and promotes pro-inflammatory macrophage polarization and antigen presentation." (PMID 41403953, 2025). "Elevated levels of YTHDF2 are implicated in modulating the tumour suppressor functions of NK cells and are linked to the final maturation stages of NK cells." (PMID 40356909, 2025). "Separately, IL-10–STAT3 signaling upregulates the m6A reader YTHDF2 in tumor-associated macrophages, and restraining YTHDF2 reprograms macrophages toward an IFN-high, antigen-supportive state and restores CD8+ T-cell activity." (PMID 41280938, 2025). "YTHDF2 modified transcripts that encode NF-κB, and controlled anti-tumor immunity by regulating intra-tumoral Tregs21." (PMID 41184358, 2025). "Within the TME, a deficiency in YTHDF2 augments the antigen‐presenting capacity of tumor‐associated macrophages (TAMs), facilitating the activation and proliferation of CD8+ T cells." (PMID 39802639, 2025). "Ythdf2 deficiency impairs T-cell function, accelerates tumor progression, and reduces responsiveness to PD-1 blockade." (PMID 41403953, 2025). "YTHDF2 modified transcripts that encode NF-κB, and controlled anti-tumor immunity by regulating intra-tumoral Tregs14,21." (PMID 41184358, 2025). "In tumor-associated macrophages (TAMs), YTHDF2 is instrumental in modulating their anti-tumor immune capabilities." (PMID 39342406, 2024). "•Induction of endoplasmic reticulum stress is the cause of YTHDF2 knockdown-induced suppression of tumor stemness and promotion of apoptosis." (PMID 38776708, 2024). "Clinical correlation analyses of TCGA data showed that YTHDF2 was highly expressed in PCa tissues and positively associated with the tumor stage and prognosis." (PMID 38962952, 2024). "YTHDF2 deficiency in TAMs suppress tumor growth and enhance cancer immunotherapy by reprogramming TAMs toward an antitumoral phenotype and increasing their antigen cross-presentation ability, which in turn enhanced CD8+T cell-mediated antitumor immunity." (PMID 38022518, 2023). "As presented in Tsuchiya K’s research, m6A RNA methylation regulators, including YTHDF1 and YTHDF2 are associated with better patient survival and therapeutic targets related to the tumor-immune microenvironment in non-small cell lung cancer." (PMID 37194014, 2023). "Consistent with the IHC observations, YTHDF2 levels were higher in tumors compared with normal tissues, and higher YTHDF2 expression was associated with higher tumor grades." (PMID 36973285, 2023). "Nevertheless, there are also examples associating a decrease in YTHDF2 expression with poor prognosis, tumor progression, and metastasis in HCC." (PMID 37369946, 2023). "Mechanistically, YTHDF2 enhanced expression of PPP2CA, the catalytic subunit of PP2A (Protein phosphatase 2A), in an m6A-independent manner, and silencing of PPP2CA antagonized the anti-tumor effects caused by overexpression of YTHDF2 in GC cells." (PMID 36870954, 2023). "Following IR, loss of Ythdf2 in myeloid cells augments antitumor immunity and overcomes tumor radioresistance by altering MDSC differentiation and inhibiting MDSC infiltration and suppressive function." (PMID 37236197, 2023). "Recently, C1Q+ TAMs have been reported to influence CD8+ T cell enrichment in tumors and Mettl14 or Ythdf2 deficiency in TAMs impedes tumor eradication by reducing cytotoxic T cell infiltration and encourage the accumulation of defective CD8+ T cells." (PMID 35538548, 2022).